PIWIL1 (piwi like RNA-mediated gene silencing 1)
Diseases named in the same sentence as PIWIL1 in open-access papers (continued):
Sharing a sentence is not in itself a finding about the gene and the disease.
tumor (continued). "On the other hand, a piRNA derived from a tumor-suppressive lncRNA and PIWIL1/4 recruit histone-modifying enzymes MLL3 and UTX (or KDM6A) to activate the transcription of TRAIL (TNF-related apoptosis-inducing ligand) leading to tumor growth inhibition." (PMID 38303021, 2024). "Recent study show that Piwi Like RNA-Mediated Gene Silencing 1 (PIWIL1) increases oxygen utilization and energy production via FAs metabolism and attracts myeloid-derived suppressor cells (MDSCs) into the tumor microenvironment, generating tumor immune suppression in HCC." (PMID 38584256, 2024). "The analysis of the mRNA expression levels of 21 CTAs in healthy and tumor ovarian tissue showed an up-regulation in the expression level of AKAP3, MAGEA4, PIWIL1, and PRAME in tumor samples and a down-regulation in the expression level of CTAG1A, CTAG1B, MAGEC1, and PIWIL2." (PMID 37835834, 2023). "Clinical studies comparing PIWIL1 levels in malignant lung tissue to levels in normal lung tissue found that PIWIL1 was detected distinctively in tumor cells, whereas it was absent in normal tissue." (PMID 36980876, 2023). "Moreover, the piRNA interacting protein Piwil1 is enriched in GSCs and maintains GSC self-renewal and Piwil1 knockdown in GBM animal model suppresses tumor growth and promotes mouse survival." (PMID 36009578, 2022). "In patients with CRC, PIWIL1 expression levels were closely related to the degree of tumor differentiation, TNM stage, the occurrence of lymph node invasion, and distant metastasis, suggesting that increased PIWIL1 expression may promote tumor invasion." (PMID 34070617, 2021). "Their results suggested that PIWIL1 can significantly boost cell proliferation, migration, tumorigenesis and metastasis by forming a complex with UPF1, UPF2, SMG1 and other components to degrade mRNAs and lncRNAs with tumor suppressor potential." (PMID 33718392, 2021). "Through bioinformatics analysis, we found the expressions of PIWIL1 and PIWIL4 were increased in GC tumour tissues as compared to the normal gastric mucosa tissues whereas the high expression of PIWIL4 in GC tumour tissues was correlation with poor OS in GC patients." (PMID 33169519, 2020). "Furthermore, PIWIL1 can induce EMT and endow endometrial cancer (EC) cells with stem-like properties, such as tumor cell viability, migration, invasion, and sphere-forming activity." (PMID 31399034, 2019). "PIWIL1 expression was also observed in tumor samples, but was not seen in any of the normal specimens." (PMID 31890151, 2019). "The results suggesting that PIWIL1 might promote the growth, proliferation, and invasion of CRC tumor cells." (PMID 28634417, 2017). "Expression of DNMT3B, PIWIL1, NANOG, OCT4, and CDH2 was significantly elevated in tumor samples compared to normal controls (p = 8.33 × 10−45, 1.01 × 10−23, 7.76 × 10−6, 3.22 × 10−54, and 1.82 × 10−22, respectively), indicating strong tumor-specific upregulation of these genes." (PMID 41596471, 2026). "Overexpression of PIWIL1 resulted in accelerated fatty acid metabolism and higher secretion of the C3 component, which subsequently could result in P38 MAPK-mediated production of IL-10 in myeloid-derived suppressor cells in the tumor microenvironment." (PMID 39596284, 2024). "Moreover, we analyzed a PIWIL1-positive and a PIWIL1-negative tumor sample by bisulfite sequencing and found differences in the degree of methylation between the two samples." (PMID 25742785, 2015). "PIWIL1 was expressed in 11 of the tumor samples but in none of the normal tissue samples." (PMID 25742785, 2015).
tumor (continued). "Besides, the treatment of etomoxir could significantly reduce the xenograft growth rate of PIWIL1-overexpressing HCC in mice, as well as the size of the tumor, although treating etomoxir may also restrict the tumor growth in wild type HCC." (PMID 33633112, 2021). "However, in humans over expression of PIWIL1 did not increase cell growth but caused programmed cell death in myeloid leukaemia KG1 cells, suggesting that PIWIL1 may prevent tumor development in these cells." (PMID 24932571, 2014). "Since we found low levels of PIWIL1 and PIWIL2 in a pancreatic normal cell line, this event seems not to be exclusive of tumor cells." (PMID 32357464, 2020). "It was observed that PIWIL1-overexpressing orthotopic tumor significantly attracted PMN-MDSCs from the circulation; however, PMN-MDSCs harbored at the liver tissues surrounding the HCC tumor without further infiltrating into the tumor tissue." (PMID 33633112, 2021).
benign tumors (2 papers, 2014 to 2020). "In this study, we investigated the expression of PIWIL1–4 and MAEL in 25 EOC, 19 benign tumor samples, and 8 normal ovarian tissues." (PMID 24932571, 2014). "The expression of PIWIL1 and MAEL however is significantly increased in malignant EOC when compared to benign tumors." (PMID 24932571, 2014). "PIWIL1 had significantly higher expression, while PIWIL2 expression was significantly lower in cancerous tumors (early and late stage) as compared to benign tumors." (PMID 33374923, 2020).
brain degeneration (2 papers, 2020 to 2022). "In control cases, without neurodegenerative diseases, cell nuclei, nuclear membranes, and cytoplasm of anterior horn cells (AHCs) were positive for PIWIL1." (PMID 35015250, 2022). "PIWIL1 is a member of the PIWI subfamily that plays important roles in stem cell self-renewal, RNA silencing, translational regulation, and neuron development, which potentially implicates multiple aspects of brain degeneration." (PMID 33213512, 2020).
pancreas (1 paper, 2020). "A second profile of expression associated variable PIWIL2 and PIWIL4 genes downregulation, an aberrant level of PIWIL1 and absence of PIWIL3 expression observed in anal canal, head and neck, cervix, skin, kidney and pancreas tumors." (PMID 33008024, 2020).
PIWIL1 also shares sentences with these, for which no sentence is quoted: esophageal squamous cell carcinoma (4 papers); testicular germ cell tumor (3); bladder cancer (2); colorectal tumors (2); pancreas adenocarcinoma (2); testicular seminoma (2); adenocarcinoma (1); Alpha Thalassemia/Mental Retardation Syndrome X-linked (1); amyotrophic lateral sclerosis (1); atrophic gastritis (1); cervical squamous cell carcinoma (1); colorectal adenocarcinoma (1); cutaneous melanoma (1); Down syndrome (1); endometrial atypical hyperplasia (1); gynecological cancers (1); head and neck cancer (1); hyperplasia (1); intestinal polyp (1); kidney cancer (1); leukemia (1); malignant glioma (1); melanoma (1); myelodysplastic syndrome (1); Obstructive azoospermia (1); oligospermia (1); osteosarcoma (1); ovarian tumors (1); polyp (1); prostate adenocarcinoma (1).
A further 7 diseases each share a sentence with PIWIL1 in 1 paper.